AR (androgen receptor)
Diseases named in the same sentence as AR in open-access papers (continued):
Sharing a sentence is not in itself a finding about the gene and the disease.
penile tumor (2 papers, 2017 to 2020). "The expression of AR was significantly decreased in penile tumors, both in the microarray and in the set of cases used for validation (p < 0.001)." (PMID 28122331, 2017). "Given the AR expression by normal penile epithelium, we determined whether AR signaling was required to sustain SA penile tumor growth by performing mock procedure or surgical castration on 8–12-week-old SA males and following the penile tumor progression for 4 weeks." (PMID 32358507, 2020). "We stained human primary penile tumor samples (n = 8) and observed pronounced nuclear AR expression in adjacent normal epithelium (5/5 cases) but not in the malignant area (8/8 cases)." (PMID 32358507, 2020). "A previous study by our group on penile tumors did not reveal AR hypermethylation." (PMID 28122331, 2017).
periodontitis (2 papers, 2011 to 2024). An acute or chronic inflammatory process that affects the tissues that surround and support the teeth. "Testosterone deprivation through both orchiectomy and chemical AR blockade with flutamide increases bone resorption in male rats under experimental periodontitis, though only orchiectomy also increases osteoclast counts." (PMID 39917660, 2024). "Research using male rat models of ligature-induced periodontitis has demonstrated the effects of testosterone manipulation, employing both surgical orchiectomy (OCX) and chemical AR inhibition." (PMID 39917660, 2024).
Peritoneal Fibrosis (2 papers, 2023 to 2024). Disorder characterized by a wide range of structural changes in PERITONEUM, resulting from fibrogenic or inflammatory processes. "BAX, PIM1, AR, and others are involved in signaling pathways such as apoptosis, cell migration, and metabolism which also involved in peritoneal fibrosis." (PMID 37266145, 2023).
phospholipidosis (2 papers, 2019 to 2020). "They illustrated a minor probability of affecting the androgen receptor and they are considered to be able to produce cardiotoxicity and phospholipidosis." (PMID 33324621, 2020). "According to our results, there is a possible inhibition of the organic anion transporting peptides OATP1B1 and/or OATP1B3, a weak potential of cardiotoxicity, a minor probability of affecting the androgen receptor, and phospholipidosis." (PMID 31552240, 2019).
Pleural effusion (2 papers, 2014 to 2017). The presence of an excessive amount of fluid in the pleural cavity. "Alike solid distant metastases, receptor conversion for ERα, PR, AR and HER2 is a frequent phenomenon in peritoneal and pleural effusion metastases." (PMID 28903441, 2017).
prostate acinar adenocarcinoma (2 papers, 2020 to 2025). "Pathology revealed metastatic prostate acinar adenocarcinoma (immunohistochemistry: CK +, P504S +, AR (androgen receptor, partially +), paired box gene (PAX)-8-, PAX-2-, MelanA-)." (PMID 41350908, 2025).
pyelonephritis (2 papers, 2024 to 2025). An inflammatory process affecting the kidney. "Of note, restoring maturation in LysM-Cre × ARf/f mice did not alter kidney bacterial burden 7 dpi, indicating that androgen-dependent susceptibility to persistent high-titer pyelonephritis is not exclusively attributable to myeloid cell AR signaling." (PMID 38206009, 2024).
rash (2 papers, 2023). "Interestingly, the other AR inhibitor enzalutamide, darolutamine, showed a low rash incidence in clinical trials." (PMID 37342589, 2023). "Unfortunately, no literature was found about the management of skin rashes due to androgen receptor-signaling inhibitors." (PMID 37118710, 2023).
retinal dystrophies (2 papers, 2023). "Even though AR has been used as a standard XCI marker for several studies, including retinal dystrophies, we herein suggest that several XCI markers should be compared with minimize the risk of false positive or false negative results." (PMID 37541846, 2023).
serous ovarian tumors (2 papers, 2017 to 2019). "However, similar to studies in TNBC, we found that average AR expression was higher in BRCA1 and BRCA2-mutated high-grade serous ovarian tumors compared to non-mutated BRCA tumors." (PMID 34926721, 2019).
skin aging (2 papers, 2021 to 2023). The gradual irreversible changes in structure of skin that occur as a result of the passage of time.. "In addition, ROC curve verified that these hub-target had certain sensitivity and specificity for the diagnosis of skin aging (AUC greater than 0.5), AR, BCEH, CXCR2, HPGD and PI3 performed well especially." (PMID 37310405, 2023). "Molecular docking analysis showed that 8 key compounds had a high docked ability with AR, BCHE, HPGD and PI3, which were identified as specific biomarker for the diagnosis of skin aging." (PMID 37310405, 2023). "Then, we confirmed the down-regulated expressions of ABCC4, PTGER3, BCEH, HPGD, and MOXD1 in normal group, while AR, CXCR2, HSD17B2, ODC1, PI3, PLAU and THBS2 were up-regulated in skin aging group." (PMID 37310405, 2023). "TF AR downregulated not only target gene TYR through triggering TF MITF to promote melanin synthesis, but also target gene CDH1, which was modified by phosphorylation, to promote cell-cycle, apoptosis and DNA damage in both middle-aged and elderly skin aging." (PMID 34073305, 2021). "In the next core pathway of both middle-aged and elderly skin aging, the ligand KITLG promotes melanin synthesis, DNA damage, and inhibits cell-cycle arrest by modulating TFs AR and MITF via signaling transduction proteins FAM83H, HSPB1, PAX3, ATF5, and H2AFB2." (PMID 34073305, 2021).
small cell lung carcinoma (2 papers, 2018 to 2025). Small cell lung cancer (SCLC) is a highly aggressive malignant neoplasm, accounting for 10-15% of lung cancer cases, characterized byrapid growth, and early metastasis. "The inhibition of androgen by castration or androgen receptor antagonist in male mice resulted in a much higher frequency of bone metastasis in small cell lung cancer mice." (PMID 30013512, 2018). "Human small cell lung cancer cell lines SBC-5, which is apt to metastasize to bone, expressed AR and ERβ, but not ERα; by contrast, human small cell lung cancer cell line SBC-3, which does not metastasize to bone, expressed ERα and ERβ, but not AR." (PMID 30013512, 2018).
soft tissue sarcoma (2 papers, 2011 to 2016). A malignant neoplasm arising from muscle tissue, adipose tissue, blood vessels, fibrous tissue, or other supportive tissues excluding the bones. "SRs, including AR, have been previously detected in a large set of human soft tissue sarcomas of different histological origin." (PMID 21359179, 2011).
Spinal bulbar muscular atrophy (2 papers, 2024 to 2025). "Spinal bulbar muscular atrophy (SBMA) is an X-linked recessive motor neuron disorder caused by the presence of ≥38 CAG repeats in the androgen receptor gene." (PMID 38323115, 2024). "Spinal bulbar muscular atrophy (SBMA), a genetic neuromuscular disorder, is a genetic neuromuscular disorder resulting from a trinucleotide repeat expansion in the androgen receptor gene." (PMID 40961031, 2025).
Swyer syndrome (2 papers, 2024 to 2025). "Intriguingly, AR RNA was found to be exceptionally elevated in blood of individuals with Swyer syndrome, and was also associated with GCTs in gonadal tissue." (PMID 38212646, 2024).
Testicular Tumor (2 papers, 2020 to 2021). "Androgen receptor was overexpressed in 10 of 13 primary testicular tumors and 2 of 5 metastatic testicular LCTs (without detectable ARv7 messenger RNA or ARv7 protein)." (PMID 33741265, 2021).
thymoma (2 papers, 2015 to 2022). A neoplasm arising from the epithelial cells of the thymus. "Preclinical data suggest that blocking AR with 5-alpha-dihydrotestosterone can initiate apoptosis in thymoma cells [S20]." (PMID 25595907, 2015).
type 1 diabetes (2 papers, 2012 to 2014). "Much of the previous experimental evidence for α- and β-AR-dysfunction has been derived from models of type 1 diabetes, and conducted in anaesthetised or isolated heart or vessel preparations." (PMID 25496763, 2014).
urothelial neoplasm (2 papers, 2015 to 2025). A neoplasm involving a urothelium. "The results of this study demonstrate that AR expression occurs in a significant fraction of urothelial neoplasms." (PMID 41463239, 2025). "Our findings demonstrate that AR is weakly expressed in normal urothelium and that AR expression is retained and perhaps even enhanced in a fraction of urothelial neoplasms, while most urothelial cancers may either downregulate or completely lose their AR expression." (PMID 41463239, 2025).
vitamin D deficiency (2 papers, 2021 to 2023). A nutritional condition produced by a deficiency of VITAMIN D in the diet, insufficient production of vitamin D in the skin, inadequate absorption of vitamin D from the diet, or abnormal conversion of vitamin D to its bioactive metabolites. "In the present study, we found that under the effect of vitamin D deficiency with unchanged androgen receptor density, the testosterone-induced relaxation was decreased in females not receiving Androgel treatment, in response to vitamin D deficiency." (PMID 38068901, 2023). "Although vitamin D deficiency did not affect androgen receptor density, it did reduce relaxation in males and non-PCOS females, whereas this reduction was absent in PCOS females." (PMID 38068901, 2023).
X-linked recessive disease (2 papers, 2021 to 2022). X-linked recessive form of disease. "SBMA, also known as Kennedy’s Disease, is an X-linked recessive disease caused by a CAG trinucleotide repeat expansion in the Androgen Receptor (AR) gene." (PMID 36143200, 2022). "AIS is an X-linked recessive disease caused by inactivating mutations in the androgen receptor (AR) gene (Xq11-q12), resulting in complete or partial resistance to the physiological effects of androgen in 46,XY individuals." (PMID 34867780, 2021).
acute liver failure (1 paper, 2013). Rapid deterioration of liver function causing encephalopathy and coagulopathy. "Distributions of patients with HBV-related acute liver failure (ALFs) and asymptomatic HBV carriers (AsCs) according to the qualitative categories of AR CAG repeats." (PMID 24391916, 2013).
adenosarcoma (1 paper, 2013). A low grade malignant neoplasm characterized by the presence of a benign epithelial component (tubular and cleft-like glands) and a low grade sarcomatous component that contains varying amounts of fibrous and smooth muscle tissues. "Immunohistochemical analysis of adenosarcoma without sarcomatous overgrowth showed expression of CD10, WT1, ER, PR, androgen receptor (AR), cytokeratin and muscle markers." (PMID 24649216, 2013).
adrenal carcinoma (1 paper, 2011). A carcinoma involving a adrenal gland. "Next, we further assessed the role of the SWI/SNF-mediated complexes in ZMIZ1 regulated AR activity using the human adrenal carcinoma cell line, SW13, which is deficient in both BRG1 and Brm expression and considered to lack functional SWI/SNF complexes." (PMID 21949845, 2011).
adrenal hypoplasia (1 paper, 2015). "Included in this group were AR, Coup-TFα, Coup-TFβ, dosage-sensitive sex reversal-adrenal hypoplasia congenital critical region on the X chromosome, gene 1 (DAX1), ERα, ERRα, HNF4γ, liver receptor homolog-1 (LRH1), NOR1, NURR1, PPARγ, RARβ, RORα, RORβ, and VDR." (PMID 26244663, 2015).
allergic rhinitis (1 paper, 2023). Inflammation of the nasal mucous membranes caused by an IgE-mediated response to external allergens. "Our data demonstrated that androgen receptor antagonist Bicalutamide can significantly alleviate allergic rhinitis lesion in the animal model." (PMID 35831673, 2023).
anorectal malformation (1 paper, 2024). "According to these results, it is suggested that the AR and the Fgf10/Fgfr2 signaling pathways could be involved in the development of anorectal malformations in male rats exposed to DBP in utero." (PMID 39728417, 2024).
anovulation (1 paper, 2023). The absence of ovulation. "This study demonstrated nuclear translocation of CK2α to phosphorylate HDAC2 is essential for ovulation, which may explain the mechanism of androgen-AR-CK2α axis-induced anovulation in PCOS patients." (PMID 37076890, 2023).
anxiety disorder (1 paper, 2022). A category of psychiatric disorders which are characterized by anxious feelings or fear often accompanied by physical symptoms associated with anxiety. "SSHs in the pathophysiology of anxiety disorders appear to include signaling in the HIP, AMY, PFC, or HPA/HPG axes via ERβ (or GPER1 concerning the antidepressant-like effects in female rats) in females and AR signaling in males." (PMID 36159923, 2022). "The relationship between the transmembrane AR ZIP9 and anxiety disorders has not yet been described." (PMID 36159923, 2022).
aphakia (1 paper, 2010). "The aphakia phenotype suggested a mutation in FOXE3 close to the AR-locus 1p34.3-p32.2, and sequence analyses revealed the nonsense mutation c.720C>A, changing cysteine 240 to a stop codon." (PMID 20361012, 2010).
arterial tortuosity syndrome (1 paper, 2023). Arterial tortuosity syndrome (ATS) is a rare connective tissue disorder characterized by tortuosity and elongation of the large and medium-sized arteries and a propensity towards aneurysm formation, vascular dissection, and stenosis of the pulmonary arteries. "Arterial tortuosity syndrome (ATORS) [OMIM:208050] is caused by an AR mutation in the SLC2A10 gene at location 20q13.12, resulting in GLUT10 deficiency." (PMID 37239976, 2023).
aspiration pneumonia (1 paper, 2026). "Patient No. 21, with 42 CAG repeats in the AR gene and with elevated pNfL levels, also exhibited a more rapid clinical decline than typically observed in SBMA, dying of aspiration pneumonia after a three-year symptomatic disease course." (PMID 41513898, 2026).
autoimmune thyroid disease (1 paper, 2024). Inflammatory disease of the thyroid gland due to autoimmune responses leading to lymphocytic infiltration of the gland. "Shorter AR (CAG)n repeats, increasing the activity of the androgen receptor, were found to predispose to a younger onset of autoimmune thyroid disease." (PMID 39204081, 2024).
basal cell adenocarcinoma (1 paper, 2017). "Among the rare types of SGC, AR expression has been reported in PLGA and basal cell adenocarcinoma (BCAC), whereas all published cases of myoepithelial carcinoma (MECA) have been AR-negative." (PMID 28208703, 2017).
Becker muscular dystrophy (1 paper, 2025). Becker muscular dystrophy (BMD) is a neuromuscular disease characterized by progressive muscle wasting and weakness due to degeneration of skeletal, smooth and cardiac muscle. "In 5 couples, both partners have P/LP variants in the same AR gene (CFTR, GJB2, ATP7B, DHCR7), and in one couple, a woman has a clinically significant variant in the DMD gene linked to Becker muscular dystrophy." (PMID 41595422, 2025).
bestrophinopathy (1 paper, 2021). "For instance, the onset of AD vitelliform macular dystrophy (OMIM #153700) associated with mutations in the BEST1 gene may vary from infancy to adulthood, while AD vitreoretinochoroidopathy (OMIM #193220) and AR bestrophinopathy (OMIM #611809) usually manifest in the first decade of life." (PMID 34946832, 2021). "When family history and clinical findings are consistent with AR bestrophinopathy and there are additional pathogenic criteria supporting that the variant might not be clinically neutral, BEST1 variants should be assigned PM2 according to the established AR cutoff (i.e., three homozygotes)." (PMID 34946832, 2021).
bone marrow failure syndrome (1 paper, 2014). "The notion that bone marrow failure syndromes, which are associated with telomere attrition, reveal premature aging also at the epigenetic level may indicate that AR-CpGs depict exhaustion of the hematopoietic stem cell pool." (PMID 24490752, 2014).
brain injury (1 paper, 2025). Acute and chronic (see also brain INJURIES, CHRONIC) injuries to the brain, including the cerebral hemispheres, CEREBELLUM, and brain STEM. "Specifically, AR is necessary for myelin regeneration and astrocyte function within the CNS, processes that require STAT3 signaling and are dysregulated after traumatic brain injury." (PMID 40117367, 2025).
carcinoid (1 paper, 2023). "Furthermore, it is important to note that uncommon histological subtypes of PCa have been reported, including double-negative (AR-, NE-), amphicrine, carcinoid, and squamous-type carcinomas." (PMID 36828904, 2023).
cataract (1 paper, 2019). Partial or complete opacity of the crystalline lens of one or both eyes that decreases visual acuity and eventually results in blindness. "AR inhibitors (ARIs) have received considerable attention because of the proposed involvement of AR in the pathophysiology of diabetic complications, including cataracts." (PMID 31130646, 2019).
chorioamnionitis (1 paper, 2022). A morphologic finding indicating inflammation of the fetal sac membranes. "Testosterone interacts with the androgen receptor (AR) that is expressed in immune cells involved in chorioamnionitis, including polymorphonuclear cells (PMN)." (PMID 35563368, 2022).
chronic granulomatous disease (1 paper, 2025). Chronic granulomatous disease (CGD) is a rare primary immunodeficiency, mainly affecting phagocytes, which is characterized by an increased susceptibility to severe and recurrent bacterial and fungal infections, along with the development of granulomas. "AR mutations in NADPH oxidase mutations result in chronic granulomatous disease (CGD), characterized by severe bacterial and fungal infections leading to repetitive abscesses associated with hyperinflammation, such as colitis with perianal lesions." (PMID 40649913, 2025).
chronic hepatitis B (1 paper, 2013). "Augmentation of androgen/androgen receptor (AR) pathway may influence chronic hepatitis B (CHB) more likely in males." (PMID 24391916, 2013). "We present here a clinical and laboratory dataset of AR CAG repeat and serum testosterone level measurements in male chronic hepatitis B patients." (PMID 24391916, 2013).
cocoon syndrome (1 paper, 2024). "Complete AR IKK-α deficiency causes the embryo-lethal cocoon syndrome, whereas AR partial IKK-α deficiency, described in four patients, can underlie syndromic ectodermal dysplasia with or without immunodeficiency." (PMID 39231201, 2024).
colitis (1 paper, 2019). Inflammation of the colon. "The role of other steroid hormone receptors such as the androgen receptor (AR) and the progesterone receptor (PR) during colitis progression have been investigated only poorly." (PMID 31139192, 2019).
coronary atherosclerosis (1 paper, 2022). Atherosclerosis of the coronary vasculature. "It was also verified that AR was crucial in mediating the effects of androgens to regulate glucose and lipid metabolisms in males and relatively early coronary atherosclerosis." (PMID 35990823, 2022).
cortical cysts (1 paper, 2013). "Positive reactions for ER alpha, AR y GPR30 were observed in epithelium of ovary sections; co-localization with cytokeratin allowed the identification of epithelial cells in the ovarian surface and cortical cysts." (PMID 24279585, 2013).
craniosynostosis (1 paper, 2023). Craniosynostosis is defined as the premature fusion of one or more cranial sutures leading to secondary distortion of skull shape resulting in skull deformities with a variable presentation. "Dysregulation of androgen hormones has previously been implicated in both syndromic and non-syndromic cases of craniosynostosis and the androgen receptor is abundantly expressed within the dura matter and calvarial bones of fetal mice." (PMID 36982425, 2023).
Crohn disease (1 paper, 2020). A gastrointestinal disorder characterized by chronic inflammation involving all layers of the intestinal wall, noncaseating granulomas affecting the intestinal wall and regional lymph nodes, and transmural fibrosis. "New AR gene subtypes undetected originally also appeared in gnotobiotic pigs, in Crohn’s Disease (CD) patients after transplant, and in feces of infant subjects." (PMID 32508773, 2020).